NOS2 (nitric oxide synthase 2)
Diseases named in the same sentence as NOS2 in open-access papers (continued):
Sharing a sentence is not in itself a finding about the gene and the disease.
osteoarthritis (12 papers, 2017 to 2023). A noninflammatory degenerative joint disease occurring chiefly in older persons, characterized by degeneration of the articular cartilage, hypertrophy of bone at the margins and changes in the synovial membrane. "Conditional deletion of Elf3 in mouse chondrocytes results in decreased IL-1β-mediated induction of Mmp13 and Nos2, and these mice undergo less cartilage loss in a model of osteoarthritis." (PMID 30200227, 2018). "In knee osteoarthritis, administration of exogenous miR-17 downregulated the expression of pathological catabolic factors such as MMP13, ADAMTS5, and NOS2, thereby reducing extracellular matrix damage and alleviating the severity of osteoarthritis." (PMID 37016437, 2023). "Nitric oxide synthetized by the inducible nitric oxide synthase (NOS2) is one of the major proinflammatory and destructive mediators in osteoarthritis." (PMID 34679766, 2021). "The most potent compound, (S)-(+)-carvone, significantly decreased the expression of NOS2 and IL-1β in macrophages and in a cell model of osteoarthritis using primary human chondrocytes." (PMID 32350292, 2020). "Our results from an in-vitro model of osteoarthritis indicate that genistein inhibits the IL-1β-induced expression of the catabolic factors nitric oxide synthase 2 (NOS2), cyclooxygenase 2 (COX-2), and matrix metalloproteinases (MMPs)." (PMID 31137797, 2019). "ELF3 levels are elevated in human cartilage from patients with osteoarthritis (OA), and ELF3 contributes to the IL-1β-induced expression of genes encoding Mmp13, Nos2, and Ptgs2/Cox2 in chondrocytes in vitro." (PMID 29691435, 2018). "Indeed, high levels of NOS2 have been found in the synovial membrane of individuals with osteoarthritis." (PMID 34679766, 2021). "The high levels of PI3K and NOS2 displayed in the periaqueductal gray matter of MIA-injected mice support the fact that this brain area regulated the nociceptive and inflammatory processes implicated in the progression of osteoarthritis pain." (PMID 34679766, 2021). "Acetylated ligstroside aglycone significantly reduced the expression of pro-inflammatory genes including NOS2 and MMP13 at both RNA and protein levels; decreased nitric oxide release; and, importantly, reduced proteoglycan loss in human osteoarthritis cartilage explants." (PMID 32523668, 2020). "Moreover, experiments performed on animals have supported this idea by showing that NOS2 inhibition could be an attractive way to treat osteoarthritis." (PMID 34679766, 2021). "ELF3 protein is overexpressed in the cartilage of patients with osteoarthritis, and drives expression of the IL-1β-induced genes MMP13, NOS2, and PTGS2/COX2 in chondrocytes." (PMID 30200227, 2018).
tuberculosis (12 papers, 2014 to 2025). A chronic, recurrent infection caused by the bacterium Mycobacterium tuberculosis. "tuberculosis-infected MiR-21−/− bone marrow derived macrophages (BMDMs) showed increased levels of pro-inflammatory mediators including nitric oxide synthase 2 (Nos2) mRNA, arginase 1 (Arg1), and ROS with concomitant containment of M. tuberculosis." (PMID 34248974, 2021). "Expression of NOS2 was elevated in the tuberculosis group but highest in the traumatized elephant (NL4)." (PMID 33195633, 2020). "Macrophages from patients with inflammatory diseases, such as tuberculosis, malaria, or rheumatoid arthritis, have increased levels of NOS2 mRNA and active protein, which may contribute to elevated plasma NO levels." (PMID 25339954, 2014).
Parkinson disease (11 papers, 2011 to 2025). A progressive degenerative disorder of the central nervous system characterized by loss of dopamine producing neurons in the substantia nigra and the presence of Lewy bodies in the substantia nigra and locus coeruleus. "If (Casp1, Ifngr, Nos2)−/− mice indeed have increased levels of dopamine and/or glutamate, they might prove useful as pre-clinical models of Parkinson’s disease." (PMID 31015500, 2019). "However, the effects of NOS2 on α-synuclein-induced Parkinson’s disease (PD) pathology remain unclear." (PMID 36647152, 2023). "However, the effects of NOS2 on the pathology of Parkinson’s disease (PD) are not well studied." (PMID 36647152, 2023).
Salmonella Infections (11 papers, 2012 to 2025). Infections with bacteria of the genus SALMONELLA. "Heat-killed KUNN19-2 upregulated Nos2 expression indifferently from its viable form in all clinical Salmonella infections." (PMID 40076451, 2025). "Phagocyte NADPH oxidase (NOX2) and inducible nitric oxide synthase (NOS2) flavohemoproteins are key host determinants in resistance to Salmonella infections." (PMID 37014914, 2023). "In Salmonella infections, the NOS2 gene expression is highly induced in tissue of infected mice but the NO subsequently produced appears to have contradictory effects." (PMID 32459575, 2020). "A previous study examined the expression of NOS2 in a high responder line versus a low responder line to Salmonella infection." (PMID 31281305, 2019). "Our results of Salmonella infection mediated upregulation of NOS2 activity in DCs are in accordance with previous reports." (PMID 30452468, 2018). "Previous reports suggest that the nitric oxide synthase 2 (NOS2) play a role in a positive regulation of FPN during Salmonella infection." (PMID 28507548, 2017). "(C–E) RT-qPCR analysis of mRNAs encoding inflammatory cytokines (Tnfα, Il1β, and Il6), chemokines (Ccr2, Ccl2, Cxcl1, and Cxcl10) and macrophage biomarkers (Nos2 and Arg1) in BMDMs measured at the indicated times after Salmonella infection (multiplicity of infection [MOI] = 1) (n = 5)." (PMID 39475776, 2024). "As observed in liver, Nos2 was also induced in BMDM after Salmonella infection." (PMID 28507548, 2017). "Viable and heat-killed KUNN19-2 enhanced the expressions of proinflammatory-related genes Mip-2 and Nos2 in RAW264.7 cells regardless of Salmonella infection." (PMID 40076451, 2025). "Next, we compared pro-inflammatory gene (Mip2 and Nos2) expressions at 1 h post-Salmonella infection in macrophages with or without KUNN19-2 pretreatment." (PMID 40076451, 2025). "In the presence of functional IL-12, the loss of IL-23 may not affect susceptibility to Salmonella infection due to enhanced IFN-γ production and accumulation of TNF and Nos2 producing cells." (PMID 22624013, 2012).
Hyperglycemia (10 papers, 2011 to 2024). An increased concentration of glucose in the blood. "The NF-κB-dependent pathway links maternal hyperglycemia to increased expression of nitric oxide synthase 2 (NOS-2) and production of reactive nitrogen species." (PMID 36140900, 2022). "Hyperglycemia also stimulates the expression of nitric oxide (NO) synthase 2 (NOS2) to produce high levels of NO and reactive nitrogen species and augment protein nitrosylation and nitration, resulting in nitrosative stress." (PMID 28824831, 2016). "Experiments using nos2 gene knockout animals demonstrate that Nos2 plays a key role in mediating the adverse effect of hyperglycemia on embryonic malformation." (PMID 26887929, 2016). "Hyperglycemia increases production of nitric oxide (NO) through NO synthase 2 (Nos2) and reactive oxygen species (ROS), generating nitrosative and oxidative stress conditions in the embryo." (PMID 26887929, 2016). "In HMVEC, we showed that the hyperglycemia induced an upregulation of NOS3 and NOS2 gene expression levels similar to previous study." (PMID 24093550, 2013).
leishmaniasis (10 papers, 2008 to 2024). Infectious disease that is transmitted through the bite of hematophagous female phlebotomine sand flies. "Latent Leishmaniasis is reactivated in chronically infected healthy C57BL/6 mice by inhibition of endogenous NOS-2, indicating that iNOS expression is crucial for the sustained control of L. major infection." (PMID 24204259, 2013). "Moreover, targeted mRNAs Ifng and Nos2 displayed upregulation and enrichment in several parasite infection pathways, including the amoebiasis, Chagas disease, leishmaniasis, and toxoplasmosis pathways." (PMID 38229193, 2024). "In humans, the involvement of NOS2 in protection against leishmaniasis has been demonstrated by the finding that higher NOS2 expression correlates with fewer parasites in localized CL, while low NOS2 expression correlates with high parasite burden in diffuse CL." (PMID 34777283, 2021). "NOS2 expression was higher in leishmaniasis than in sporotrichosis lesions." (PMID 29440688, 2018). "Macrophages, the main effector cells in leishmaniasis, can be instructed to kill or to promote the growth of intracellular Leishmania parasites, depending on the balance of two inducible enzymes, nitric oxide synthase 2 (NOS2) and arginase." (PMID 18478052, 2008).
type 2 diabetes (10 papers, 2014 to 2025). "In turn, polymorphisms in NOS2 are associated with a higher plasma glucose concentration and variants in the promoter sequence of this gene also correlate with type 2 diabetes." (PMID 33374571, 2020). "Nitric oxide synthases (NOS1, NOS2, and NOS3) and myeloperoxidase (MPO), which have been implicated in the development of type 2 diabetes, are also important ROS-generating enzyme families." (PMID 36902173, 2023). "NOS2 protein expression is high in pancreatic islets of patients with type 2 diabetes (T2D) and inhibition of NOS2 expression restores disturbed GSIS." (PMID 33374571, 2020).
breast tumors (9 papers, 2012 to 2025). "NOS2 expression in ER- breast tumors is associated with poor patient outcomes and a basal-like phenotype, linking NO signaling to this poor outcome and highly metastatic phenotype." (PMID 22971289, 2012). "Logistic regression analysis of IHC results for the breast tumors showed that the association between NOS2 and pAkt-(ser473) was strongest in tumors with elevated TIMP-1 protein but reduced in those with low TIMP-1 expression." (PMID 22957045, 2012). "Also, a pro-inflammatory microenvironment associated with tumor derived NOS2 directly correlated with tumor pAkt status and downstream signaling including p-caspase-9 and pBAD in the same breast tumors." (PMID 22957045, 2012). "Since breast tumors, differently from other cancer types, more rarely harbor Ras mutations, the S-nitrosylation of Ras and thus the activation of Ets1 signaling axis may indeed explain the wild-type Ras-mediated tumorigenesis of cancers overexpressing NOS2." (PMID 30155439, 2018). "We have recently demonstrated a requirement of IFN-γ–associated with stroma-restricted CD8+ T cells for tumor NOS2 and COX2 expression in ER– breast tumors that is higher in tumors from deceased patients." (PMID 40663402, 2025). "This pattern is suggestive of increased cancer stemness and is consistent with earlier reports of elevated CD44 levels in high NOS2-expressing ER- breast tumors." (PMID 37169743, 2023). "Given that increased stem cell biomarker expression was observed in high NOS2 expressing ER- breast tumors, we measured CSC biomarker expressions (ALDH1A1, OCT4, CXCR4, CD133, CD117, CD44 and NANOG) in the control and DETANO treated MCF10A cells." (PMID 36830680, 2023). "Previous research also found that MDSCs from CCL5-knockout mice with breast tumors expressed less NOS2 and S100A8/9 and showed an immune-stimulatory phenotype." (PMID 34566958, 2021). "A direct correlation between NOS2 expression and elevated Akt phosphorylation status has been observed in breast tumors." (PMID 22957045, 2012). "A significant enrichment of genes with EBS was found among the genes that were up-regulated in the NOS2 high tumors, confirming that NOS2 and Ets-regulated genes are correlated in ER- breast tumors." (PMID 22971289, 2012). "Because TIMP-1 mediates Akt signaling and is also regulated by NO we explored the relationship between TIMP-l, NOS2, and Akt phosphorylation signaling in the same breast tumors." (PMID 22957045, 2012). "A significant relationship between NOS2 expression and Akt phosphorylation (NOS2/pAkt) was reported for these breast tumors." (PMID 22957045, 2012). "Thus, spatially distinct NOS2 and COX2-expressing cells in relation to CD8+ T cells in aggressive breast tumors suggest an association between CD8+ T cells and cytokine-induced NOS2/COX2 niches that influence clinical outcomes." (PMID 37169743, 2023). "Thus, TIMP-1 constitutes an additional marker of tumor aggressiveness and poor disease outcome for which NOS2 correlates in these breast tumors." (PMID 22957045, 2012). "Tumor NOS2 expression was moderately to strongly expressed in 70% of all (ER+ and ER−) tumors, whereas only a few tumors (10%–20%) showed marked NOS2 expression in infiltrating CD11b+ immune cells, implicating the tumor epithelium as the major source of NOS2-derived NO in breast tumors." (PMID 39356141, 2024). "Together, this work demonstrates that targeting NOS2 and COX2 together augments antitumor immune responses of aggressive ER– breast tumors." (PMID 40663402, 2025). "As previously shown by us, elevated tumor COX2 expression correlates with abated CD8+ T-cell infiltration into breast tumors, whereas stroma-restricted CD8+ T cells correlate with both increased tumor NOS2 expression and tumor budding or satellitosis." (PMID 39356141, 2024).
breast tumors (continued). "Moreover, the robust association between NOS2 expression and up-regulation of genes with EBS transcriptional activation sites in microdissected and bulk tumor epithelia indicates that Ets-1 is a significant in vivo mediator of NOS2 signaling in human ER- breast tumors." (PMID 22971289, 2012). "In addition, cytokines that were upregulated in high NOS2-expressing ER-breast tumors, including IL6 and IL8, were induced by these treatments and correlated with NOS2/COX2 expression." (PMID 37169743, 2023). "Our study indicates that tumor NOS2/COX2 expression plays a central role in tumor immune evasion, suggesting that strategies combining clinically available NOS2/COX2 inhibitors with immune therapy could provide effective options for the treatment of aggressive and drug-resistant ER– breast tumors." (PMID 40663402, 2025).
inflammatory bowel disease (9 papers, 2015 to 2025). A spectrum of small and large bowel inflammatory diseases of unknown etiology. "In the intestinal epithelium, the upregulation of NOS2 and the consequent chronic release of NO at high concentrations have been associated with the pathogenesis of inflammatory bowel disease (IBD), mainly through the generation of peroxynitrite." (PMID 37175841, 2023). "Although NOS2 polymorphisms have also been linked to chronic inflammatory diseases such as inflammatory bowel disease (IBD), the role of rs2297518 may differ in acute settings." (PMID 41226345, 2025). "For instance, NOS2 may reduce HF and liver injury by reducing inflammatory responses, and studies has shown that NOS2 may reduce inflammatory bowel disease and maintain gut microbial homeostasis." (PMID 36687648, 2022). "If NOS2 is not properly regulated by these factors, its excessive activity can contribute to the onset and progression of conditions such as inflammatory bowel disease (IBD)." (PMID 39839550, 2024).
ovarian carcinoma (9 papers, 2008 to 2024). A malignant neoplasm originating from the surface ovarian epithelium. "The addition of 1400W, an iNOS inhibitor, to OVCAR-3 and Caov-3 ovarian cancer cell cultures or their treatment with NOS2 siRNA significantly reduced cell growth." (PMID 30970628, 2019). "In ovarian cancer, downregulation of PDLIM2 promotes tumor growth by modulating NOS2-derived nitric oxide signaling and the recruiting M2 type macrophages." (PMID 38880883, 2024). "PRMT5, PRMT1, DDAH1, DDAH2, NOS2, ARG1, and ARG2 were all found to be up-regulated in the stage I/II or stage III/IV ovarian cancer tissues compared to normal tissues." (PMID 37684587, 2023).
pancreatic cancer (9 papers, 2011 to 2025). "This rescue experiment demonstrates that the regulation of NOS2 and •NO in pancreatic cancer cells is controlled by NRF2, or more comprehensively, the KRAS-NRF2 axis." (PMID 40567499, 2025). "Of the three known isoforms, inducible NOS (iNOS or NOS2) can increase the aggressiveness of pancreatic cancer cells." (PMID 40567499, 2025). "In fact, in gastrointestinal tumors treated with Th2 cells, we noted enhanced production of MPO and NOS2, which has cytotoxic effects on colon and pancreas cancer cells as we have previously noted." (PMID 36376448, 2023). "In pancreatic carcinoma, NOS2 enhances tumor aggressiveness by activating kynurenine metabolic signaling." (PMID 37795447, 2023). "NOS2 was expressed in the Cancer Cell Line Encyclopedia (CCLE) pancreatic cancer cell lines, therefore it is not only present in stromal and immune cells but also in the tumor cells." (PMID 27762323, 2016). "Notably, 8‐OHG released under GPX4 deficiency activates the STING (stimulator of IFN genes) pathway, driving aberrant expression of inflammatory mediators such as IL‐6 and NOS2 (nitric oxide synthase 2), providing new insights into pancreatic cancer inflammatory microenvironment formation." (PMID 40919133, 2025). "Pancreatic cancer cells, for example, are often found in a hypoxic microenvironment characterised by a specific genetic signature: overexpression and constitutive activation of KRAS, overexpression of NRF2 and HIF-1, and restricted expression of NOS2." (PMID 40567499, 2025).
prostate carcinoma (9 papers, 2014 to 2023). A carcinoma that arises from epithelial cells of the prostate gland. "On the contrary, CDK19 and NOS2, overexpressed during prostate cancer progression, were induced in NE-like tumors and down-regulated in DHT-treated OSC." (PMID 32041153, 2020). "MDSCs in prostate cancer tissues can upregulate cationic amino acid transporter 2 (CAT2), ARG‐1, and nitric oxide synthase 2 (NOS2) expression, decreasing l‐arginine production, increasing nitric oxide (NO) production, and enhancing the detrimental effects on T cells." (PMID 37547175, 2023).
pulmonary fibrosis (9 papers, 2014 to 2025). Chronic progressive interstitial lung disorder characterized by the replacement of the lung tissue by connective tissue, leading to progressive dyspnea, respiratory failure, or right heart failure. "Masson’s trichrome staining for collagen, a fibrosis marker, showed increased collagen staining in KA/KA lungs compared to WT and that NOS2 deletion reduced collagen expression, indicating that induced NOS2 contributes to the development of lung fibrosis." (PMID 29844930, 2018). "By analyzing the target interaction network VCAM1,RELA,CDK2,JUN,CDK1,HSP90AA1,NOS2, SOD1,CASP3,AHSA1, PTGER3 are at the core of the network, which can be regarded as the key targets of Astragalus polysaccharides in treating pulmonary fibrosis." (PMID 35370663, 2022). "CAV1, NOS2, GDF15, and CDKN2A were demonstrated to be influencing the development of pulmonary fibrosis by regulating ferroptosis." (PMID 35069688, 2021). "CAV1, NOS2, GDF15, CDKN2A may influence the development of pulmonary fibrosis by regulating ferroptosis." (PMID 35069688, 2021).